CDH1 (cadherin 1)
Diseases named in the same sentence as CDH1 in open-access papers (continued):
Sharing a sentence is not in itself a finding about the gene and the disease.
tumor (continued). "Given the existing germline mutation in CDH1, the cancer genome only requires a second allelic hit via a somatic genetic aberration, as is demonstrated in the tumor from this individual." (PMID 25315765, 2014). "CTNNB1 and CDH1 are crucial components of cell-cell adhesion complexes, and their loss has often been associated with tumor metastasis and poor clinical outcome." (PMID 24971456, 2014). "We sought to study this reciprocal regulation in cell lines derived from ILBC, a tumor entity associated with CDH1 inactivation." (PMID 24023670, 2013). "We determined the relevance of this new concept in human infiltrating lobular breast cancer (ILBC), the prime tumor entity associated with CDH1 inactivation." (PMID 24023670, 2013). "A recent study has shown that PTEN can interact with anaphase-promoting complex/cyclosome (APC/C), an E3 ubiquitin ligase, and promote its association with cadherin 1 (CDH1), thereby enhances the tumor-suppression activity of the APC-CDH1 complex." (PMID 23514585, 2013). "Studies have demonstrated that EMT and the resultant loss of CDH1 expression are crucial steps in tumor progression and correlate with poor clinical outcomes." (PMID 22613095, 2012). "Decreased CDH1 expression at the tumor periphery has been linked to increased metastasis-risk and decreased overall patient survival." (PMID 22613095, 2012). "This oncogenic EMT is typified by increased invasion and metastatic dissemination, therapeutic resistance and loss of expression of tumor suppressors such as CDH1." (PMID 22613095, 2012). "The second tumour harboured a novel CDH1 missense mutation in exon 9 (Patient 11) at nucleotide position c1223 that changes codon 408 from alanine to valine." (PMID 22152101, 2011). "Both tumours (with CDH1 missense mutation in exon 9) occurred in two female patients with peritoneal carcinogenesis." (PMID 22152101, 2011). "CDH1 is considered to be a tumour suppressor gene, whose loss has also been demonstrated to promote tumour invasion and metastasis in various cancer models." (PMID 21639893, 2011). "CDH1 missense mutations in exon 9 were detected in 2 of 22 tumours (9%), and several polymorphisms were found in 4 of 22 tumours (18%)." (PMID 22152101, 2011). "All OTBCs exhibited a complete loss of epithelial markers associated with tumor suppressive functions, such as E-cadherin (CDH1) and Maspin, and a gain of mesenchymal markers, such as VIM and neural cell adhesion molecule (N-CAM)." (PMID 21952072, 2011). "The first tumour showed a CDH1 missense mutation in exon 9 (Patient 27) at nucleotide position c1204 that changes codon 402 from aspartic acid to histidine, thereby affecting the putative calcium-binding motif DAD (DAD > DAH)." (PMID 22152101, 2011). "The CDH1 missense mutations occurred in 2 out of 15 tumours (13%) of these histological subtypes and were diffuse-type signet cell ring gastric carcinomas." (PMID 22152101, 2011). "While disrupted cell-cell adhesion caused by the reduced expression of Cdh1 and/or desmosomal genes (this report) clearly promotes invasive tumor growth, other factors are involved as well." (PMID 20862307, 2010). "While LBC tumors are generally considered “cold” due to low tumor mutational burden and limited immune infiltration, recent evidence suggests that CDH1 loss may alter immune cell composition within the tumor microenvironment." (PMID 40757085, 2025). "Therefore, CDH1 methylation is not only a hallmark event of tumor invasion and metastasis but also reflects the functional cross-talk between epigenetic regulation and immune evasion." (PMID 41394878, 2025). "The CDH1 gene encodes a glycoprotein, E-cadherin, which acts as a tumor suppressor." (PMID 39859345, 2025). "Furthermore, genetic mutations are also critical contributors—for example, Cadherin 1 (CDH1) gene mutations in diffuse GC reduce intercellular adhesion, enabling tumor cells to invade and metastasize more readily." (PMID 40756989, 2025).
tumor (continued). "The proband’s mother, a 45-year-old, visited the Cancer Hospital of the Chinese Academy of Medical Sciences on February 17, 2023, for tumor genetic susceptibility gene testing: a heterozygous pathogenic mutation in exon 12 c.1921C>T (p.G1n641 *) of CDH1 was detected." (PMID 41378303, 2025). "Loss of CDH1 disrupts these structures, resulting in poorly cohesive tumor cells." (PMID 40757085, 2025). "In addition, E‐cadherin (CDH1) is a protein that is associated with tumour invasiveness and tumour progression." (PMID 40374531, 2025). "Of note, in hereditary diffuse gastric cancer, the role of TRAF2 in promoting EMT could be particularly important since this tumor displays E-cadherin gene (CDH1) germline or somatic mutations, which correlate with increased aggressiveness and poor prognosis." (PMID 40229245, 2025). "Decreased CDH1 expression is associated with cancer initiation and progression, and impairment of this gene augments the invasive and metastatic abilities, consequently hastening the progression of the tumor." (PMID 39619995, 2024). "CDH1 or E-cadherin, is a tumour suppressor gene associated with various cancers." (PMID 39421182, 2024). "In the current study, we tested a large series of women with diagnosed LBC fulfilling the HLBC clinical criteria, aiming to assess the frequency of germline variants in the CDH1 gene, genomic inactivation in matched tumor samples, and disease-free and overall survival." (PMID 38652475, 2024). "In sporadic LBC (germline CDH1 VUS or LB), discordances between germline and tumor testing were observed in 2 of 7 cases (28.6%), including 1 germline intronic CDH1 variant (c.2295+16C>A) and 1 germline CDH1 copy number variant ([?_68768071]_[68869950_?]dup) missed by tumor sequencing." (PMID 38652475, 2024). "Furthermore, the abnormal upregulation of vimentin and downregulation of CDH1 have been associated with tumour recurrence and impaired hypothalamic function following surgical intervention in patients with ACP." (PMID 38594611, 2024). "CDH1, a tumor suppressor gene on chromosome 16q22.1, encodes a 120 kDa protein called E-cadherin." (PMID 39390525, 2024). "CDH1 target profiles may provide a link between E-cadherin loss and the mesenchymal phenotype acquired by tumor cells in response to NAC." (PMID 37322261, 2024). "These phenomena might suggest that E-cadherin loss/CDH1 mutations could promote tumor initiation through impairing DDR pathways." (PMID 39349771, 2024). "Moreover, mutation analysis of the hub genes of the N list showed that CDH1 has a higher mutation rate in tumour samples (9%)." (PMID 37118990, 2023). "The results showed that Cdh1, Fas, and Satb2 were strongly associated with neoplasms, whereas Fas was related to immune system diseases and nervous system diseases, hinting that they might have a stronger correlation with CIPN." (PMID 37623249, 2023). "In addition to well-known EMT inhibitors, such as CDH1 (encoding E-cadherin), the downregulated subset also included genes with tumor suppressor activity and poorly characterized roles in EMT." (PMID 37176013, 2023). "Finally, IFITM2, a pro-apoptotic gene, encoding a protein which has been linked to protection against tumour proliferation, was found downregulated in the CDH1-TANGO6 deletion clone." (PMID 37249750, 2023). "In the present study, we tested this hypothesis and found that co-treatment with ROS1 inhibitors and FAK inhibitors conferred synergistic anti-tumor effects in CDH1-deficient mice model of DGC in vitro and in vivo." (PMID 37324948, 2023). "Silencing of CDH1 is linked to advanced tumor stage and an aggressive character." (PMID 37046772, 2023). "CDH1 is a tumor suppressor gene located on chromosome 16q22.1, which encodes E-cadherin." (PMID 37393258, 2023).
tumor (continued). "Lack of CDH1 expression results in loss of contact inhibition and cell polarity, metastases, invasion, tumor proliferation, activation of motility, and migration, which also correlate with the development and progression of primary tumors and183, 185 tumor dedifferentiation." (PMID 37901797, 2023). "CDH1 was known as a tumor suppressor, and germline mutations may inactivate CDH1, which will result in tumor progression and migration." (PMID 35498538, 2022). "However, a separate study, which also reported a similar case, demonstrated that both the tumor’s solid-papillary and classic lobular components shared a common CDH1 mutation and a number of copy number alterations." (PMID 35096664, 2022). "CDH1 mutant tumours showed a higher mutational burden indicative of APOBEC-mediated mutagenesis." (PMID 35053458, 2022). "Besides, infiltrative tumor growth pattern and lymph node metastasis were associated with loss of CDH1 expression in CRC." (PMID 36161592, 2022). "Studies in tumor-derived cell lines and organoids highlighted additional invasion and cell growth phenotypes associated with malignant transformation and identified key mediators, including Myc and Cdh1." (PMID 35703180, 2022). "Conversely, FAP-positive tumour cells expressed significantly lower levels of genes encoding epithelial junction proteins (including CDH1, JUP, CTNN1A) epithelial differentiation markers, including several keratins (6B, 7, 17, 19, 23) and mucins (1, 3A, 4, 12), and chemokines (CXCL1-3, 5, 6)." (PMID 35296803, 2022). "LBC is the second most frequent tumor phenotype associated with germline CDH1 mutations." (PMID 35277969, 2022). "Similarly, in case 2, LBC seems due to both the germline pathogenic variant of the CDH1 gene, followed by a possible loss of the second allele in tumoral DNA, which represents the second hit of CDH1 tumor suppressor gene inactivation process." (PMID 35686104, 2022). "The loss of Cdh1 expression impairs adhesion of primary tumor cells in many cancers, including PCa." (PMID 37305018, 2022). "CDH1 was downregulated and associated with large size (>5 cm) of tumor." (PMID 34679042, 2021). "To determine whether primary signet ring cell/histiocytoid carcinoma harbors the CDH1 mutation or other actionable mutations, we analyzed the tumor tissue via next-generation sequencing." (PMID 33617508, 2021). "For example, cell membrane-associated tumor suppressors such as Cadherin-1 and beta-catenin play important roles in maintaining cell adhesion, and loss of their PM localization and nuclear accumulation is present in a wide variety of solid tumors and is associated with poor prognosis." (PMID 33879063, 2021). "Furthermore, in several human cancer types, in parallel to E-cadherin loss, the de novo expression of mesenchymal cadherins, such as N-cadherin and cadherin-11, is observed during tumor progression." (PMID 34680444, 2021). "Moreover, there were significant associations between CDH1 promoter methylation, stage, grade, lymph node metastasis, and tumor size." (PMID 33883026, 2021). "Cadherin 1 (CDH1) gene encoding E-cadherin protein that is responsible for cell–cell adhesion, is a tumor suppressor gene related to the PI3/Akt/mTOR pathway and widely researched in BC with the evidence that downregulation is associated with poor prognostic parameters." (PMID 34679042, 2021). "Downregulation of CDH1 has been associated with large tumor size." (PMID 34679042, 2021).
tumor (continued). "MSI findings in the CDH1 gene may indicate increased genome instability, which, in the early stages of tumorigenesis, accelerates the process of tumor cell evolution by accumulating mutations." (PMID 33915799, 2021). "Clearance of Cdh1/E-cadherin-deficient cells by cell death prevents tumor formation." (PMID 34359596, 2021). "CDH1 is a tumor suppressor gene, so any mutation resulting in its loss of function can cause derangements in the basic cellular structure of the tissues resulting in a neoplasm or an irregular growth which can later develop into a malignancy." (PMID 33062523, 2020). "The CDH1 gene is located on chromosome 16q22.1 and encodes the E-cadherin, a transmembrane calcium-dependent protein involved in cell-cell adhesion, acting as a tumor suppressor that prevents invasiveness and metastatization." (PMID 32046255, 2020). "CDH1 mutations were also significantly more frequent in tumours with signet ring cells (p = 0.043)." (PMID 31949278, 2020). "Furthermore, loss of SIRT2 and the resulting impaired activity in both APCCDH1 and APCCDC20 complexes, or the loss of CDH1 itself, promotes genomic instability and tumor progression, indicating that generalized APC dysfunction is tumorigenic." (PMID 32805721, 2020). "Finally, our patient’s tumor demonstrated a deleterious mutation in CDH1 exon 12 leading to early truncation of the CDH1 protein, similar to the findings of our previous study." (PMID 31638990, 2019). "We hypothesized that CDH1 loss creates vulnerabilities in a tumor cell that can be specifically targeted with drugs using a synthetic lethal approach." (PMID 31467357, 2019). "We postulate that tumor cells might utilize oncogenic potential to overcome Cdh1-deficiency caused genomic stress while taking advantage of the elevated Cdh1 downstream targets to facilitate their growth and metastasis." (PMID 31420536, 2019). "Inactivation of CDH1 is described to be prominently associated with tumor invasiveness, metastatic dissemination, and poor patient prognosis; the significance of CDH1 expression for metastatic potential has been shown in a variety of in vitro and in vivo models." (PMID 29080283, 2018). "Thus, the CDH1 mutations appeared to be associated with three cancer-related processes—the canonical cancer driver pathway, cell–cell adhesion, and the tumor microenvironment." (PMID 29520031, 2018). "E-cadherin (CDH1) is a putative tumor suppressor gene implicated in breast carcinogenesis." (PMID 29700408, 2018). "For example, higher H3K36me3 levels induces increased skipping of the final 83 base pairs of CDH1 exon 8, resulting in cell discohesion, which may be an underlying mechanism of a relatively high tumor stage in H3K36me3-positive HCC." (PMID 30356299, 2018). "We performed Single Sample Gene Set Enrichment Analysis (ssGSEA) for tumour samples with high and low expression levels of CDH1, termed as CDH1-high and -low, with two gene sets associated with oestrogen signal transduction, ESTROGEN_RESPONSE_EARLY and ESTOGEN_RESPONSE_LATE." (PMID 29527007, 2018). "E-cadherin is an important tumour suppressor and its expression is frequently lost in cancer via genetic mutation or epigenetic silencing of the CDH1 gene encoding E-cadherin or alternatively via activation of various signalling pathways resulting in its downregulation." (PMID 28430163, 2017). "Diffuse tumours are seen in hereditary diffuse gastric cancer which is associated with germline E-cadherin gene (CDH1) alterations however reasons for the higher incidence of sporadic diffuse cancers in Māori remain unclear." (PMID 28732086, 2017). "E-cadherin (CDH1) involves in many important cellular processes including cell-cell interactions, cell development and genetic changes of this molecule has been associated with greater tumor metastasis." (PMID 29285016, 2017).
tumor (continued). "In thousands of primary carcinomas, we found that the prevalence of tumors with CDH1 or CTNNB1 mutations appear to be too low to explain most clinically-observed cases of cancer cell detachment from the primary tumor (i.e. regional or distant tumor spread)." (PMID 29156750, 2017). "Interestingly, hypermethylation was demonstrated to be the most frequent cause of a second-hit CDH1 inactivation in HDGC tumours, whereas a second mutation or deletion is apparently less frequent." (PMID 29231860, 2017). "Finally, we tested for possible associations between CDH1 expression levels and CDH1a presence/absence with patients’ clinical parameters including tumor stage, grade and size, as well as 5-years disease-free survival and presence of H. pylori." (PMID 27861150, 2017). "The high expression of CDH1 is associated with group I tumours." (PMID 27607470, 2016). "The tumor suppressor gene CDH1 encodes the cell adhesion molecule E-cadherin." (PMID 27863424, 2016). "It is known that mutations in CDH1 increased proliferation and tumor invasion and metastasis." (PMID 25807360, 2015). "We reviewed the DNA copy number status at the CDH1 gene locus in the 153 lobular tumours from The Cancer Genome Atlas (TCGA) data resource and this revealed that 12.4% of tumours show a diploid copy number; 84.3% show a single copy loss and 3.3% show a putative homozygous deletion." (PMID 25849106, 2015). "CDH1 is a tumor suppressor gene that encodes epithelial cadherin." (PMID 26484312, 2015). "Mutations in CDH1 gene affect protein integrity, thus causing disturbances in cell-cell adhesion in epithelial tissues, increasing cell motility and enhancing infiltrative behavior of the tumor and metastasis development." (PMID 25180051, 2014). "The regulatory component of this complex, Cdh1, has been shown to be downregulated during malignant progression in a murine B lymphoma cell line and mice heterozygous for cdh1 are more susceptible to spontaneous tumor formation." (PMID 24280138, 2013). "This reciprocal regulation may be a critical determinant of early tumor development following CDH1 inactivation or loss of E-cadherin expression." (PMID 24023670, 2013). "This is as well the only tumour for which CDH1 is mutated (Gln23* nonsense mutation)." (PMID 24069272, 2013). "Indeed, suppression of Cdh1 has been linked to many cancers, and Cdh1 has been proposed to be a haploinsufficient tumor suppressor since Cdh1 heterozygotic mice are more likely to develop spontaneous epithelial tumors." (PMID 22479455, 2012). "Moreover, the expression of CTNNB1 and CDH1 were significantly associated with early tumor recurrence." (PMID 22962603, 2012). "Because cytogenetic complexity is associated with tumor progression in pRCC, the alternative acquisition of promoter methylation at CDH1 and RASSF1A loci might characterize a different subset of pRCC with less aggressive clinical behavior." (PMID 17645803, 2007). "Differential CpG island methylation in the promoter region of the CDH1 gene might be an alternative way for the loss of expression and function of E-cadherin, leading to loss of tissue integrity, an essential step in tumor progression." (PMID 16512896, 2006). "Furthermore, liquid biopsy approaches leveraging circulating tumor DNA to detect CDH1 mutations non-invasively may facilitate early detection of recurrence and real-time monitoring of treatment response." (PMID 40757085, 2025). "In the tumor, we observe a loss of the E-cadherin protein due to the inactivation of CDH1 gene by combining a first hit, mainly a truncating variant to a second hit causing the methylation of CDH1 promotor (50%) or a loss of heterozygosity in favor of the pathogenic first hit (50%)." (PMID 41154377, 2025).